IL6 (interleukin 6)
Diseases named in the same sentence as IL6 in open-access papers (continued):
Sharing a sentence is not in itself a finding about the gene and the disease.
Cerebral ischemia (continued). "The most important cytokines related to inflammation in cerebral ischemia include IL-1β, TNF-α, IL-6, IL-10, and transforming growth factor-β (TGF-β)." (PMID 35656190, 2022). "Brain ischemia significantly upregulated mRNA expression of TNF‐α, IL‐1β, and IL‐6, which were inhibited by BMPER." (PMID 34904361, 2022). "In the study of cerebral ischemia-reperfusion injury, the expression of TNF-α, IL-1β, and IL-6 was significantly decreased after Acacetin treatment compared with the middle cerebral artery occlusion group." (PMID 34594156, 2021). "However, some other studies also show that the early intravenous or intracerebroventricular injection of recombinant IL-6 can improve cerebral ischemia, and the IL-6 signaling component, gp130, may mediate neuroprotective and anti-inflammatory effects against cerebral ischemia." (PMID 34943061, 2021). "Many investigations have documented that IL-6 signaling has protective and not only detrimental effects, e.g., IL-6 counteracts NMDA receptor-mediated excitotoxicity following brain ischemia and also promotes nerve regeneration." (PMID 33923626, 2021). "In the striatum, we have shown that relative expression of Nt‐3, Nestin, β‐actin, Tnfα, Il‐1β, Il‐6, and Il‐10 increased whereas expression of Bdnf, Gdnf, Vegf, and β‐III tubulin decreased after cerebral ischemia." (PMID 32281225, 2020). "Electroacupuncture alleviates cerebral inflammation in cerebral ischemia/reperfusion injury through the TLR4/NF-κB pathway, which is accompanied with the suppressed secretion of the inflammatory cytokines TNF-α, IL-1β and IL-6." (PMID 32479555, 2020). "During cerebral ischemia, activated microglial cells migrate to inflammatory sites and produce excessive neurotoxic and inflammatory mediators, such as TNF-α, IL-1β, IL-6, MCP-1, MIP-1, PGE2 and NO, which exacerbate neuronal damage." (PMID 33373319, 2020). "Cerebral ischemia results in activation of NF-κB in microglia which release inflammatory factors, such as TNF-α, ICAM-1, IL-6." (PMID 32153408, 2020). "Dexmedetomidine pretreatment attenuated neurological injury, brain lesions and expression of inflammatory factors (IL-1β, IL-6, TNF-α) after brain ischemia (P < 0.05)." (PMID 33287729, 2020). "Reperfusion after cerebral ischemia (R/I) in MetS rats increased MDA, TNF-α, and IL-6 levels, but it decreased the activities of the main scavenger enzymes including SOD, CAT, and GSH-Px and neuron densities in CA2 and CA3 subregions of the hippocampus." (PMID 30937145, 2019). "The most important cytokines that are related to inflammation in cerebral ischemia are IL-1, TNF-α, IL-6, IL-10, and transforming growth factor-β (TGF-β)." (PMID 29540536, 2018). "TNF-α, IL-6, MCP-1, VEGF, and MMP expression induced by cerebral ischemia was abrogated in Poldip2+/− mice." (PMID 29452577, 2018). "Among them, TNF-α, IL-1β and IL-6, iNOS and COX-2 are all dynamically altered in different stages of brain ischemia-reperfusion, and they usually bring detrimental effect to brain and BBB." (PMID 30622459, 2018). "The aSAH patients usually develop cerebral ischemia within two weeks after bleeding; the DCI is also developed late, and it has been reported that IL-6 levels tend to rise immediately before DCI." (PMID 29194369, 2017). "NF-κB is involved in the inflammatory responses that potentiate cerebral ischemic damage, thus activating many genes involved in the pathogenesis of cerebral ischemia, such as iNOS, IL-1β, TNF-α, ICAM-1, COX-2, and IL-6." (PMID 29220411, 2017). "Here, these pro-inflammatory cytokines (IL-1β, IL-6, and TNF-α) were chosen as markers to evaluate the inhibition of the inflammatory response at 24 h after cerebral ischemia and reperfusion in the hippocampus." (PMID 28769792, 2017).
Cerebral ischemia (continued). "TCMs effectively ameliorate cerebral I/R injury by downregulating TLR4, TNF-α, IL-1β, IL-6, iNOS, COX-2, and 5-LO expression and upregulating IL-10 expression in the ischemic area during the acute and subacute phases of cerebral ischemia." (PMID 27703487, 2016). "During cerebral ischemia, proinflammatory mediators such as TNF-α, IL-1β, and IL-6 are excessively produced by a variety of activated cell types, including microglia, endothelial cells, astrocytes, and neuron cells, which finally exacerbated neuronal injury." (PMID 27123035, 2016). "During brain ischemia, proinflammatory cytokines such as TNF-α, IL-1β, IL-6, and chemokines such as CINC and MCP-1 are produced by a variety of activated cell types, including endothelial cells, microglia, astrocytes, and neurons." (PMID 25888869, 2015). "Cerebral ischemia/reperfusion leads to release of pro-inflammatory mediators (TNF-α and IL-6) which in turns leads to production of MMP by resident and infiltrating cells, which altogether increase BBB permeability." (PMID 24465746, 2014). "Induction of cerebral ischemia increased the TNF-α, IL-6 and IL-1β mRNA expression levels significantly at 4 and 24 h in the left ischemic hemispheres in the hypoxia group compared with those in the control group." (PMID 24520277, 2014). "Maddahi and Edvinsson demonstrated that U0126 significantly inhibits the iNOS, IL-6, and TNF-α secretion in rat model of cerebral ischemia." (PMID 23671886, 2013). "After cerebral ischemia (i.e., DHCA), IL-6 levels significantly increased from arterial to venous (median arterial 16 pg/ml (0.6 to 22); venous 19 pg/ml (1.1 to 39); P = 0.03)." (PMID 23390999, 2013). "Regarding the soluble effects of cerebral ischemia, although subtle, significant differences were found after DHCA in IL-6 and sVCAM-1." (PMID 23390999, 2013). "Accordingly, TNFα, IL-6 and IL-1β have been shown to correlate to the severity of SAH, cerebral vasospasm, development of late cerebral ischemia and secondary brain damage in primate." (PMID 23259581, 2012). "The observed decrease in brain levels of G-CSF and IL-6 in MyD88−/− mice, along with the reported lack of protection against cerebral ischemia in IL-6-deficient mice, may explain, in part, the absence of protection against cerebral ischemia in these mice reported in our previous studies." (PMID 22799573, 2012). "Our data suggest for the first time that the enhanced expression of iNOS, IL-1ß, IL-6 and TNF-α in cerebral ischemia is a transcription/translational event in brain vessels, and points to a way to modify their expression by MEK/ERK1/2 inhibition." (PMID 20187933, 2010). "In a diabetic rat model of cerebral ischemia–reperfusion, administration of Res at a dose of 20 mg/kg effectively reduced levels of malondialdehyde (MDA), TNF-α, IL-6 and myeloperoxidase (MPO), while increasing levels of catalase (CAT), superoxide dismutase (SOD), and IL-10." (PMID 41601537, 2026). "IL6 binds to IL6R, activating downstream JAK-STAT and MAPK signaling pathways, which in turn promotes the production of inflammatory factors and the infiltration of inflammatory cells, ultimately exacerbating neural damage following cerebral ischemia." (PMID 39847586, 2025). "After cerebral ischemia, GDLM mitigates damage brought on by inflammation and oxidative stress, lessens production of inflammatory mediators like IL-6, IL-8, and CRP, and avoids oxygen radical-induced cell membrane damage, which lowers the rate of neuronal apoptosis." (PMID 38584838, 2024). "Collectively, our study suggests that skimmianine may alleviate cerebral ischemia/reperfusion injury by modulating immune and inflammatory responses, as well as antioxidant mechanisms mediated by IBA-1, IL-6, and NF-κB." (PMID 39057078, 2024). "Furthermore, IL-1β, IL-6 and TNF-α mRNA levels were enhanced after cerebral ischemia‒reperfusion injury, consistent with previous reports." (PMID 37248543, 2023).
Cerebral ischemia (continued). "In our study, the results demonstrated that the number of TUNEL-positive cells, Bax, cleaved caspase-3, cleaved caspase-9, PARP, IL-1β, IL-6 and TNF-α protein expression were enhanced after cerebral ischemia‒reperfusion injury, while antiapoptotic Bcl-2 protein expression was decreased." (PMID 37248543, 2023). "In addition, the αHMGB1 antibody suppressed pathways of secondary inflammatory responses, such as IL-6 and TNF-α, after cerebral ischemia." (PMID 36678774, 2022). "Our results showed that Tanshinone IIA could inhibit the expression of pro-inflammatory factors TNF-α, IL-6, and IL-1β and regulate the levels of SOD and MDA in the brain tissue of rats with cerebral ischemia." (PMID 33953677, 2021). "Most importantly, elevated IL-6 CSF (rather than serum) levels appear to correlate with delayed cerebral ischemia (DCI, “vasospasm”) and secondary (“vasospastic”) infarctions." (PMID 33923626, 2021). "The release of IL-6 and TNF-α by area(s) of brain ischemia enhances the invasion of neutrophils into the brain, which intensifies the blood–brain barrier permeability, and an increased number of neutrophils in the blood is associated with the extent of the infarction." (PMID 33922467, 2021). "Treatment with melatonin could suppress the levels of IL-6, TNF-α, and IL-1β in animal models of brain ischemia/reperfusion injury, subarachnoid hemorrhage, and traumatic brain injury." (PMID 34685627, 2021). "Upregulation of IL-17 mRNA can induce the expression of IL-1, IL-6, IL-8, TNF-α, and ICAM-1, which may aggravate the secondary inflammatory reaction after cerebral ischemia." (PMID 32194375, 2020). "The results showed that BZP improved focal cerebral ischemia-reperfusion injury in rats and PC12 cells treated with Na2S2O4 in dose/concentration-dependent manners through inhibition of production of 15-HETE and expression of NF-κB, IL-6, TNF-α, and ICAM-1." (PMID 32153408, 2020). "Cerebral ischemia may damage cell membranes of neurons and glial-cells, leading to the release of TNF-α, IL-1β, and IL-6." (PMID 32848589, 2020). "Patients affected by cerebral ischemia, compared to the control group, had an increased quantity of cytokines and adhesion molecules in plasma, such as E-selectin, P- selectin, V-CAM-1, ICAM-1, IL-1, IL-6, and TNF-α." (PMID 32899616, 2020). "Inflammatory responses (such as the release of proinflammatory cytokines interleukin-1 β (IL-1β), IL-6, and tumor necrosis factor (TNF-α)) increase the expression of adhesion molecules in white blood cells and vascular endothelial cells after brain ischemia and reperfusion." (PMID 29540536, 2018). "Both IL-6 and TRPM7 are up-regulated in cerebral ischemia and are known to contribute to neuronal damage, but it is unknown whether these two molecules interact during this process." (PMID 27010689, 2016). "This was consistent with our experimental results and also been supported by a publication concerning the negative influence of miR-22 on IL-6 in rat and cell models of cerebral ischemia-reperfusion injury." (PMID 25826372, 2015). "However, interleukin-6 (IL-6) and tumor necrosis factor-α (TNF-α), two inflammatory cytokines that are accumulated during cerebral ischemia, play a protective role in the incidence of HIE." (PMID 25187835, 2014). "IL-6 up-regulates the expression of adhesion molecules, such as intercellular adhesion molecule-1 (ICAM-1), selectins and integrins on endothelial cells, leukocytes and platelets, during cerebral ischemia, which leads to secondary neuronal damage." (PMID 23497639, 2013). "We assessed the inflammation in the cerebral circulation by characterization of neutrophils and monocytes and measurement of cytokines IL-1β, IL-6, IL-8, IL-10, TNFα, sVCAM-1 and MCP-1, as these markers are known to respond within hours after cerebral ischemia." (PMID 23390999, 2013).
Cerebral ischemia (continued). "First, it has been reported that cerebral ischemia also induces activation of astrocytes, another resident cells in the brain, which can produce the proinflammatory cytokines including TNF-α, IL-1β and IL-6." (PMID 24349350, 2013). "We demonstrate that neuroprotection with D-JNKI1 after experimental cerebral ischemia is independent of systemic and brain release of interleukin-6 and keratinocyte-derived chemokine." (PMID 22533966, 2012). "Double fluorescence analysis revealed colocalizations of IL-6 with GFAP and NeuN within the ipsilateral cerebral cortex and infarcted core indicating that IL-6 is particularly expressed by astrocytes and neurons after cerebral ischemia." (PMID 22031820, 2011). "Cytokines that participate in the inflammation after cerebral ischemia include the neurotoxic cytokines interleukin-1β (IL-1β), tumor necrosis factor-alpha (TNF-α), neuroprotective cytokines interleukin-6 (IL-6), interleukin-10 (IL-10) and transforming growth factor-β." (PMID 21740583, 2011). "TNFα, IL-1β, IL-6 and MCP-1 expression was substantially upregulated after brain ischemia." (PMID 22196138, 2011). "Furthermore, our observations suggested that SMJF Granule might ameliorate cerebral ischemia–reperfusion injury by modulating key targets such as HIF-1α, IL-6, and NF-κB1, which are enriched in the HIF-1 signaling pathway." (PMID 38600597, 2024). "Pro-inflammatory microglia, by secreting cytokines such as interleukin-1β (IL-1β), interleukin-6 (IL-6), tumor necrosis factor-α (TNF-α), inducible nitric oxide synthase (iNOS), and Fc gamma RII/RIII (CD16/32), induce further inflammation and accelerate the pathological course of cerebral ischemia." (PMID 37908731, 2023). "In models of cerebral ischemia and neuronal cultures, EGCG promotes neuronal protection regulated by the Nrf2/HO-1 pathway by attenuating both ROS production and nuclear factor κB (NF-κB) activation, which consequently suppresses the expression of TNFα, IL-1β, IL-6, and iNOS." (PMID 32466215, 2020). "However, cerebral ischemia had no significantly effects on the mRNA and protein expression of IL-6 in C3H/HeJ mice (P > 0.05)." (PMID 31133816, 2019). "However, the elevation of IL-6 levels was also correlated with increased clinical severity and poorer outcomes in control patients, showing that this biomarker is not specific to cerebral ischemia." (PMID 25086655, 2014). "Importantly, our results show that neuroprotection mediated by D-JNKI1 after cerebral ischemia is independent of the early systemic release of IL-6 and KC, and reveal a later secretion from the brain." (PMID 22533966, 2012). "It is notable that cerebral ischemia did not change the levels of plasma proinflammatory cytokines TNF-α and IL-1β, but significantly increased the levels of plasma IL-6 and C-reactive protein, which were attenuated by propofol treatment." (PMID 24349350, 2013). "IL-6, Glutamate and TNF-α are not specific for cerebral ischemia either in humans or in rats." (PMID 25086655, 2014). "IL-6, glutamate and TNF-α levels were not higher in cerebral ischemia than in controls." (PMID 25086655, 2014). "The results show that brain KC and IL-6 production, although regulated by JNK, is not affected by these JNK inhibitors after cerebral ischemia and suggest that neuroprotection through JNK inhibition occurs independently of IL-6 and KC in this model and at the time points investigated." (PMID 22533966, 2012). "Similarly, IL-6, Glu and TNF-α are non-specific to cerebral ischemia in biomarker studies in rats." (PMID 25086655, 2014).
glioblastoma (249 papers, 2001 to 2026). The most malignant astrocytic tumor (WHO grade IV). "Actually, single‐cell and proteomic analyses have indicated that FOSL1 is associated with stemness through the IL‐6 pathway in glioblastoma." (PMID 41556041, 2026). "The genes encoding these proteins are more upregulated in and IL-6 more secreted from glioblastoma cells expressing US28-PDCT-Rluc compared to US28-Rluc expressing cells." (PMID 40661420, 2025). "High IL-6 gene expression in glioblastoma is associated with poor survival according to the datasets derived from The Cancer Genome Atlas (TCGA) and the Repository of Molecular Brain Neoplasia Data." (PMID 38003396, 2023). "The results of the ROC, AUC, and RR analysis of IL-1β, IL-6, IL-8, and IL-10 indicated a potential diagnostic value for clinical prognosis in patients with glioblastoma (RR > 2)." (PMID 38003396, 2023). "IL-6 production is characteristic of glioblastoma cells, and its upregulation is associated with activation and repolarization of tumor-associated neutrophils." (PMID 38003396, 2023). "IL-6 within the glioblastoma TME is secreted by tumour cells, GAMs and tumour-associated endothelial cells, and its expression can be enhanced by hypoxia, chemotherapy and radiotherapy." (PMID 33803414, 2021). "Specifically, gene amplification of IL6 has been associated with poor patient survival in glioblastoma." (PMID 34313788, 2021). "IL6Ra is a receptor for IL6, with elevated levels of IL6 in glioblastomas associated with poor survival in patients." (PMID 32299465, 2020). "For example, in the glioblastoma microenvironment, IL-6 and CSF-1, which are produced by glioblastoma-associated endothelial cells, increase arginase-1 expression, which is mediated by HIF-2α activation in monocyte-derived macrophages." (PMID 32655574, 2020). "IL-6 is implicated in the regulation of VEGF secretion from glioblastoma cells, and VEGF can induce vascular permeability, which contributes to decreasing serum albumin levels." (PMID 28548947, 2017). "To determine whether activation of Gq-coupled receptors in astrocytes can similarly stimulate the release of LIF and IL-6, we screened for the presence of functional Gq-linked receptors in two glioblastoma/astrocytoma cell lines, U87-MG and 1321-N1." (PMID 39684791, 2024). "As IL-1β and IL-6 are associated with glioblastoma angiogenesis, we confirmed that KDELC2 suppression could inhibit the expression of some angiogenic factors, such as FGF and VEGF." (PMID 37107298, 2023). "For example, glioblastoma-derived immunomodulatory factors such as IL-6 and TGF-β have been implicated in the direct impairment of T-cell function and thus may limit the successful implementation of CAR-T therapy." (PMID 38132354, 2023). "Moreover, high gene expression of the pleiotropic cytokine IL-6 which suppresses T cell functions was associated with poor survival in glioblastoma patients." (PMID 35954362, 2022). "IL6, an important inflammatory cytokine, is linked to tumorigenesis, angiogenesis, and predicts poor prognosis in patients with various types of malignant tumor such as glioblastoma." (PMID 33576874, 2021). "Therefore, when IL-6 is knocked out in glioblastoma-associated endothelial cells, glioblastoma-bearing mice display an increased survival rate." (PMID 32655574, 2020). "Similarly, senescence-associated secretory factors IL-6 and IL-8, which are known to be elevated in glioblastoma cells undergoing senescence, were significantly elevated by two to three-fold in the A172 and/or U251 cell lines." (PMID 27783662, 2016). "IL-6 may represent a prognostic factor in glioblastoma patients because high IL-6 gene expression was associated with poor survival according to the datasets derived from The Cancer Genome Atlas (TCGA) and the Repository of Molecular Brain Neoplasia Data (REMBRANDT)." (PMID 33803414, 2021).